RCC2 (regulator of chromosome condensation 2)
Diseases named in the same sentence as RCC2 in open-access papers (continued):
Sharing a sentence is not in itself a finding about the gene and the disease.
gastric cancer (11 papers, 2013 to 2025). A primary or metastatic malignant neoplasm involving the stomach. "RCC2, together with PAK4, were co-immunoprecipitated with CORO1C, whereas knockdown of PAK4 ceased the association of CORO1C with RCC2 in gastric cancer cells." (PMID 35593474, 2022). "Once phosphorylated, PAK4 is released from microtubule, and then is recruited by CORO1C to the leading edge and regulates the CORO1C/RCC2 (regulator of chromosome condensation 2) complex, leading to the migration of gastric cancer cells." (PMID 35593474, 2022). "Loss of RCC2 decreased RALA activity, and inhibition of RALA via the non-specific RAL inhibitor RBC8 reduced proliferation, migration, and invasion of gastric cancer cell lines." (PMID 35626682, 2022). "Once phosphorylated, PAK4 is released from microtubules, and then is recruited by CORO1C to the leading edge and regulates the CORO1C/RCC2 complex, leading to the migration of gastric cancer cells." (PMID 35593474, 2022). "In advanced gastric cancer, miR-29c was significantly down-regulated, leading to RCC2 over-expression, and the expression of the RCC2-specific siRNA in these cells resulted in increased cell death and decreased proliferation." (PMID 29321004, 2018). "Another research group verified the downregulation of miR-29c in gastric cancer patients and assessed proliferation and colony formation ability of miR-29c by targeting RCC2." (PMID 28173777, 2017). "Identified miR-29c targets include CDK6 in RCC2 in gastric carcinoma, TIAM1 in nasopharyngeal carcinomac and mantle cell lymphoma." (PMID 29262657, 2017). "Together with the data reported previously by other groups, our results suggest that RCC2 contributes to the proliferation of gastric carcinoma cells by regulating progression of the cell cycle." (PMID 23442884, 2013). "Future studies examining the mechanism of miR-29c downregulation and the function of RCC2 in cell cycle regulation will be required in order to clarify the significance of miR-29c-RCC2-dependent cell cycle regulation in gastric carcinoma cells." (PMID 23442884, 2013). "We have found that miR-29c was downregulated in a substantial proportion of gastric carcinomas and suppressed proliferation of gastric carcinoma cells, potentially by targeting RCC2." (PMID 23442884, 2013). "We further determined whether the interaction between PAK4 and RCC2 is necessary for the migration of gastric cancer cells by transwell assay using cells with knockdown ofPAK4 orRCC2." (PMID 35593474, 2022). "Recently, miR-29 was reported to regulate gastric cancer cell proliferation by targeting RCC2." (PMID 28460450, 2017). "In this study, we showed for the first time that RCC2 is upregulated in gastric carcinoma tissues." (PMID 23442884, 2013). "Our findings indicate that miR-29c may have tumor-suppressive functions in gastric carcinoma cells, and that its decreased expression may confer a growth advantage on tumor cells via aberrant expression of RCC2." (PMID 23442884, 2013). "Therefore, we can hypothesize that decreased expression of miR-29c results in enhanced expression of RCC2, and confers a growth advantage on gastric carcinoma cells." (PMID 23442884, 2013). "Therefore, we propose that miR-29c may have a tumor-suppressive role in gastric carcinoma cells, and that its decreased expression may confer a growth advantage on tumor cells at least partly via aberrant expression of RCC2, one of the target genes of miR-29c." (PMID 23442884, 2013). "Studies by Wang and colleagues demonstrated that RALA interacts with RCC2 in SGC-7901 and MGC-803 human gastric cancer cells." (PMID 35626682, 2022). "Elevated expression of RCC2 was correlated with poor prognosis in basal cell carcinoma (BCC) 19, colorectal cancer 20, gastric cancer 21, lung cancer 22-24 and ovarian cancer." (PMID 31839818, 2019).
gastric cancer (continued). "To clarify this issue, we analyzed the expression levels of RCC2, PPIC and CDK6 mRNAs in gastric carcinoma tissues and normal epithelial tissues using quantitative RT-PCR." (PMID 23442884, 2013). "RCC2 and PPIC were actually upregulated in gastric carcinoma tissues, and therefore both were identified as possible targets of miR-29c in gastric carcinoma." (PMID 23442884, 2013). "GST pull-down assay showed that though RCC2 interacted with CORO1C∆CE, the membrane co-localization of RCC2 with CORO1C∆CE disappeared, while further PAK4 knockdown also ceased both the interaction of RCC2 with CORO1C and the leading edge co-localization of RCC2 in gastric cancer cells." (PMID 35593474, 2022). "Thus, our data suggest that miR-29c reduces the expression of RCC2 in gastric carcinoma cells, leading to suppression of their growth, not through induction of apoptosis but by a cell cycle regulation signal." (PMID 23442884, 2013). "Furthermore, knockdown of RCC2 induced growth suppression without caspase activation in gastric carcinoma cells." (PMID 23442884, 2013). "This suggests that RCC2 and PPIC may be the target of miR-29c in gastric carcinoma, whereas CDK6 may not." (PMID 23442884, 2013).
lung carcinoma (11 papers, 2016 to 2025). "In lung cancer and ovarian cancer, RCC2 suppresses cell apoptosis and enhances the sensitivity of chemotherapy drugs via activating Rac1/JNK pathway." (PMID 38993556, 2024). "RCC2 expression in lung cancer and ovarian cancer were studied using immunochemistry stain of tumor tissue arrays." (PMID 29321004, 2018). "In summary, our studies found that RCC2 is often overexpressed in lung cancer and ovarian cancer, and RCC2 expression in cancer cells altered their sensitivity to drug-induced cell death, probably because of its interaction with cellular Rac1 activity." (PMID 29321004, 2018). "Moreover, lncRNA LCPAT1 mediates smoking or PM 2.5-induced autophagy and epithelial–mesenchymal transition via RCC2, implying the possible role of lncRNA in rendering lung cancer cells into a more invasive state." (PMID 36105077, 2022). "We found RCC2 over-expression in majority of lung cancer and ovarian cancer in this study." (PMID 29321004, 2018). "RCC2 expression in lung cancer and ovarian cancer was evaluated by IHC of tissue microarrays." (PMID 29321004, 2018). "The overexpression of RCC2 occurred in lung cancer and ovarian cancer, and their sensitivity to drug-induced cell death was altered by RCC2 expression in cancer cells, indicating that RCC2 may function as an effective marker for forecasting chemotherapeutic reaction." (PMID 38008751, 2023). "Consequently, lncRNA ENST00000439577, which influences the Ral signalling pathways via RCC2, may be a potential therapeutic target for the treatment of lung cancer." (PMID 27849024, 2016). "A recent report showed that PM2.5 upregulated autophagy, migration, invasion and EMT to promote lung cancer progression via inducing IncRNA LCPAT1 and regulator of chromosome condensation 2 (RCC2)." (PMID 31420013, 2019). "In another study, lncRNA LCPAT1 was found to be involved in cigarette smoke extract (CSE) /PM2.5-induced lung cancer cell autophagy and EMT via RCC2 up-regulation." (PMID 31839818, 2019). "In 120 cases of human lung cancers including various types (LC2083; Biomax), 106 (88.3%) had RCC2 expression at +~+++, and 14 of them had - or −/+ (11.7%)." (PMID 29321004, 2018). "In an immunohistochemistry evaluation of tissue microarray, RCC2 was over-expressed in 88.3% of primary lung cancer and 65.2% of ovarian cancer as compared to non-neoplastic lung and ovarian tissues, respectively." (PMID 29321004, 2018).
ovarian carcinoma (10 papers, 2015 to 2024). A malignant neoplasm originating from the surface ovarian epithelium. "The interaction between RCC2 and RalA is implicated in chemoresistance of ovarian cancer." (PMID 33521058, 2020). "Therefore, RCC2 and associated proteins are potential therapeutic targets for treatment of ovarian cancer." (PMID 33521058, 2020). "The significant role of reduced miR-331-3p expression on the stimulation of proliferation, migration and invasion of ovarian cancer cells by directly targeting and inhibiting RCC2 was also confirmed." (PMID 38473390, 2024). "In recent years, it has been shown that RCC2 is a potent biomarker for hepatocellular and ovarian cancers." (PMID 36441563, 2022). "Decreased expression of miR-331-3p promotes growth of ovarian cancer cells by reducing expression levels of RCC2." (PMID 33521058, 2020). "High expression level of RCC2 is reported in lung and ovarian cancers, where it functions as a GEF for Rac1, which is subsequently involved in superoxide-induced cell death." (PMID 33521058, 2020). "Expression level of RCC2 is significantly higher in DDP-resistant ovarian cancer cells compared with DDP-sensitive ones." (PMID 33521058, 2020). "RCC2-RalA signaling pathway promotes ovarian cancer cell proliferation, migration, and inhibits apoptosis." (PMID 33521058, 2020). "Furthermore, RalA knockdown activates DDP-resistant ovarian cancer apoptosis, which is inhibited by overexpression of RCC2." (PMID 33521058, 2020). "In addition, RCC2 interacts with RalA and regulates RalA signaling pathway, resulting in cisplatin-resistance in ovarian cancer." (PMID 33521058, 2020). "In addition, RCC2 promotes cisplatin-resistance in ovarian cancer by regulating RalA signaling pathway." (PMID 33521058, 2020). "However, increased RCC2 expression levels in ovarian cancer restores capacity of cell proliferation, migration, and invasion inhibited by miR-331-3p." (PMID 33521058, 2020). "RCC2 play an oncogenic role by promoting proliferation and migration of DDP-resistant ovarian cancer cell lines and inhibiting cell apoptosis by regulating RalA signaling pathway." (PMID 33521058, 2020). "A previous study reports that expression level of RCC2, RalA, and RalBP1 is significantly higher in DDP-resistant ovarian cancer cell lines compared to the DDP-sensitive tissues." (PMID 33521058, 2020). "Although RCC2 promotes cell migration, by inducing EMT through activation of the Wnt-signaling pathway, it has been reported to promotes metastasis of ovarian cancer." (PMID 33521058, 2020). "In an ovarian cancer tissue array (OV208), increased RCC2 expression (++ ~ +++) was detected in 92 of 141 cases of ovarian cancers (65.2%); and 62 of them had RCC2 at +++ (44%)." (PMID 29321004, 2018).
lung adenocarcinoma (8 papers, 2018 to 2024). A carcinoma that arises from the lung and is characterized by the presence of malignant glandular epithelial cells. "Elevated RCC2 expression is closely linked to the advanced tumor metastasis and unfavorable prognosis in lung adenocarcinoma." (PMID 36441563, 2022). "In lung adenocarcinoma, RCC2 promote cell metastasis via activating MAPK-JNK signal pathway to enhance EMT progression." (PMID 38993556, 2024). "KM survival analysis demonstrated that RCC2 expression was correlated with unfavorable prognosis in lung adenocarcinoma." (PMID 36441563, 2022). "Study showed that overexpression of RCC2 promotes cell movement and induces tumor metastasis of lung adenocarcinoma by inducing epithelial-mesenchymal transition." (PMID 33170908, 2020). "A previous study shows that RCC2 overexpression promotes metastasis of Lung Adenocarcinoma (LUAD) by inducing Epithelial-Mesenchymal Transition (EMT) through modulation of mitogen-activated protein kinase-c-Jun N-terminal kinase (MAPK -JNK) signaling pathway." (PMID 33521058, 2020). "RCC2 was also reported to play a pivotal role in lung adenocarcinoma metastasis by inducing EMT via activation of MAPK-JNK signaling." (PMID 29321541, 2018).
prostate carcinoma (7 papers, 2023 to 2025). A carcinoma that arises from epithelial cells of the prostate gland. "Similarly, the top gene set whose GSAS was different between resistant and sensitive metastatic prostate samples to abiraterone treatment was driven by KNSTRN, ECT2 and RCC2 genes, three genes previously associated with prostate cancer progression." (PMID 38597610, 2024). "A study focusing on prostate cancer revealed that HH was the predominant signaling pathway affected by RCC2 knockdown in DU145 cells." (PMID 41427028, 2025). "In prostate cancer, RCC2 enhances cell proliferation and migration via modulating Hh/GLI1 signaling pathway." (PMID 38993556, 2024). "In this study, we aim to explore the possible role of RCC2 in PCa progression, in order to find new ways for prostate cancer therapy." (PMID 38008751, 2023).
colorectal cancer (6 papers, 2018 to 2024). A primary or metastatic malignant neoplasm that affects the colon or rectum. "RCC2 is a highly conserved protein implicated in prognosis of colorectal cancers, including microsatellite instable (MSI) tumors and microsatellite stable (MSS) tumors." (PMID 33521058, 2020). "Conversely in colorectal cancer, reduced RCC2 expression was associated not only with improved survival in microsatellite instable (MSI) patients, but also with poor prognosis in microsatellite stable (MSS) group 20." (PMID 31839818, 2019). "Contradictorily, increased RCC2 expression is associated with favorable prognosis in a subgroup of colorectal cancer with microsatellite stability." (PMID 29321004, 2018). "However, studies report that RCC2 is implicated in colorectal carcinomas through MSI induced by DNA mismatch repair (MMR) deficiency." (PMID 33521058, 2020). "In colorectal cancer, downregulation of RCC2 leads to microsatellite instable tumor arrest at the G2-M phase and amplify cell apoptosis." (PMID 38434981, 2024).
acute myeloid leukemia (5 papers, 2022 to 2025). Acute myeloid leukemia (AML) is a group of neoplasms arising from precursor cells committed to the myeloid cell-line differentiation. "Additionally, IGF2BP3 stimulates tumorigenesis by RCC2 in acute myeloid leukemia." (PMID 38355626, 2024). "IGF2BP3 enhances the stability of RCC2 mRNA by reading the m6A modification sites, thereby reducing AML cell apoptosis and promoting the progression of acute myeloid leukemia." (PMID 37298373, 2023). "In acute myeloid leukemia, IGF2BP3 is indispensable for leukemia cell survival by enhancing RCC2 expression through the interaction between IGF2BP3 and m6A sites in RCC2 mRNA." (PMID 37280679, 2023). "In acute myelogenous leukemia, IGF2BP3 was observed to enhance the stability of RCC2 mRNA by reading m6A modification sites, thereby promoting cancer progression." (PMID 37298373, 2023).
hepatocellular carcinoma (5 papers, 2020 to 2024). A malignant tumor that arises from hepatocytes. "Moreover, a recent study reported that RCC2 promotes development of hepatocellular carcinoma (HCC), especially during tumor invasion, and is implicated in cisplatin resistance." (PMID 33521058, 2020). "In hepatocellular carcinoma, RCC2 facilitates cell metastasis and DDP resistance via activating AKT signal pathway." (PMID 38993556, 2024). "In hepatocellular carcinoma, increased expression of RCC2 promoted HCC cell invasion and chemoresistance to cisplatin." (PMID 36441563, 2022). "In hepatocellular carcinoma (HCC), increased expression of RCC2 facilitated HCC cell invasion and chemoresistance to cisplatin." (PMID 38008751, 2023). "Therefore, RCC2 plays a role in early recurrence of melanoma, and hepatocellular carcinoma." (PMID 33521058, 2020).
glioblastoma (4 papers, 2018 to 2023). The most malignant astrocytic tumor (WHO grade IV). "In glioblastoma, RCC2 is implicated in tumor proliferation, tumorigenicity, and promoting radio-resistance by activating DNA methyltransferase 1 (DNMT1) transcription in a p-STAT3 dependent manner." (PMID 33521058, 2020). "Furthermore, elevated RCC2 was associated with an inferior prognosis in glioma patients and increased radioresistance in glioblastoma tumor cells through the activation of DNMT1 transcription." (PMID 36441563, 2022). "RCC2 promotes radio-resistance and propagation in glioblastoma by transcriptionally stimulating DNMT1 in a STAT3-dependent manner." (PMID 38008751, 2023). "This is consistent with a report that a Rac1 inhibitor (equivalent of RCC2 overexpression) increased the sensitivity of glioblastoma cell lines to Camptothecin." (PMID 29321004, 2018). "In another study on glioblastoma (GBM), expression of RCC2, the activity of the cell cycle, mismatch repair, and JAK-STAT pathways were significantly increased, implying that RCC2 plays a role in radioresistance." (PMID 33521058, 2020).
colon cancer (3 papers, 2018 to 2024). "A recent study found RCC2 as a target gene for DNA mismatch repair (MMR) deficiency in colon cancer." (PMID 29321004, 2018). "It has been shown that RCC2 can be used as a prognostic marker in the MSI subgroup in colon cancer." (PMID 36441563, 2022).
esophageal cancer (3 papers, 2022 to 2025). A primary or metastatic malignant neoplasm involving the esophagus. "Previous research reports showed that the regulator of chromosome condensation 2 (RCC2) is essential for stabilization and transcriptional activation of Sox2 and its overexpression is associated with cell proliferation, migration, and tumor promotion in esophageal cancer." (PMID 40725242, 2025). "In esophageal cancer, it has also been discovered that RCC2 accelerates cancer growth and invasion by boosting proliferation, transformation, and migration by inhibiting SOX2 ubiquitination-mediated proteasomal degradation." (PMID 36441563, 2022). "However, some studies also found that RCC2 played a role in promoting tumor growth and invasion in breast and esophageal cancers." (PMID 36441563, 2022). "RCC2 can also upregulate and stabilize SOX2 (SRY-box transcription factor 2) expression by inhibiting ubiquitination-mediated proteasome degradation, thus facilitating the progression of esophageal cancer." (PMID 39908861, 2025).
basal cell carcinoma (2 papers, 2018 to 2019). A carcinoma involving the basal cells. "By genotyping 930 patients with cutaneous basal cell carcinoma (BCC) and 33,117 controls, a single nucleotide polymorphism (SNP) rs7538876, which is located in the vicinity of RCC2, was associated with increased risk of BCC by 2.98 times as compared to non-carriers." (PMID 29321004, 2018).
breast infiltrating ductal carcinoma (2 papers, 2020 to 2024). "The immunoreactive score analysis indicated that breast invasive ductal carcinomas exhibited significantly increased RCC2 expression compared with that in the normal breast tissue samples (p < 0.001)." (PMID 32565805, 2020). "Thirty-two (93.7%) breast infiltrating ductal carcinoma samples showed significant RCC2 expression." (PMID 32565805, 2020).